IER2 (immediate early response 2)
Description:
DNA-binding protein that seems to act as a transcription factor. Involved in the regulation of neuronal differentiation, acts upon JNK-signaling pathway activation and plays a role in neurite outgrowth in hippocampal cells (By similarity). May mediate with FIBP FGF-signaling in the establishment of laterality in the embryo (By similarity). Promotes cell motility, seems to stimulate tumor metastasis.
Synonyms: ETR101; CHX1
Tractability: PROTAC: ubiquitination databases record sites on it.
Gene: Protein-coding gene on chromosome 19 (13,150,411 to 13,156,981, forward strand). Ensembl gene ENSG00000160888.
Subcellular location: Cytoplasm; Nucleus
Subcellular location (Human Protein Atlas): Nucleoplasm
Gene Ontology:
Molecular function: protein binding
Biological process: cell motility; positive regulation of transcription by RNA polymerase II; neuron differentiation; response to fibroblast growth factor
Cellular component: cytoplasm; nucleoplasm; nucleus
Genetic constraint (gnomAD): Loss-of-function variants: 0 observed, 3.09 expected, observed/expected ratio (o/e) 0, 90% interval 0 to 0.95. That is too few expected variants to judge how well the gene tolerates losing a copy. Missense variants: 372 observed, 291.52 expected, observed/expected ratio (o/e) 1.28, 90% interval 1.17 to 1.39. Synonymous variants: 198 observed, 138.21 expected, observed/expected ratio (o/e) 1.43, 90% interval 1.27 to 1.61.
Homologues: Orthologues: chimpanzee IER2 (99% identical), dog IER2 (88% identical), pig IER2 (88% identical), mouse Ier2 (79% identical), rat Ier2 (79% identical), tropical clawed frog ier2 (30% identical), zebrafish ier2b (26% identical). Paralogues in human: IER5 (36% identical), IER5L (26% identical).
Diseases named in the same sentence as IER2 in open-access papers:
IER2 is named in the same sentence as 21 diseases in open-access papers, as found by Europe PMC text mining. Sharing a sentence is not in itself a finding about the gene and the disease. The quoted sentences say what the papers report.
melanoma (4 papers, 2021 to 2025). A malignant, usually aggressive tumor composed of atypical, neoplastic melanocytes. "We found that increased IER2 expression in human melanoma is associated with shorter overall survival, and subsequently investigated the mechanisms through which IER2 exerts this effect." (PMID 34611309, 2021). "Furthermore, IER2 expression is associated with enhanced OPN expression in human melanoma and also correlates with poor prognosis." (PMID 34611309, 2021). "Thus, similar to our previous work with pancreatic tumor cells, IER2 expression is associated with enhanced invasiveness of melanoma cells." (PMID 34611309, 2021). "In the present study, we report that IER2 expression can be constitutively increased in human melanomas and that this correlates with poor overall survival." (PMID 34611309, 2021). "Overall, these data suggest that IER2 expression leads to stochastic senescence development in a fraction of melanoma cells, which elicits the production of OPN." (PMID 34611309, 2021). "Together, our study reveals that sustained IER2 expression drives melanoma invasion and progression through stimulating osteopontin secretion via the stochastic induction of senescence." (PMID 34611309, 2021). "By contrast, deletion of OPN completely abrogated the ability of wild-type IER2 to promote melanoma cell invasion." (PMID 34611309, 2021). "Together, these results demonstrate that IER2 fosters melanoma cell migration and invasion in a manner that requires nuclear localization of the IER2 protein." (PMID 34611309, 2021). "This revealed significantly higher IER2 expression in melanoma cells that exhibited an intermediate or invasive phenotype." (PMID 34611309, 2021).
melanoma (continued). "IER2 induces senescence in only a subpopulation of melanoma cells, despite the fact that all cells induced with RSL express IER2." (PMID 34611309, 2021). "Kaplan–Meier analysis revealed that melanoma patients with high IER2 expression had a significantly shorter overall survival compared to patients with lower IER2 levels." (PMID 34611309, 2021). "In line with previous results, IER2 induction markedly increased the percentage of enlarged senescent melanoma cells in the flow cytometry." (PMID 34611309, 2021). "Together, these data suggest that the IER2-dependent SASP in B16 melanoma cells includes OPN, CXCL15, CCL5, IL-6, and IL-23a." (PMID 34611309, 2021). "Similarly, IER2 has also been shown to promote invasion and metastasis in melanoma and colorectal cancer." (PMID 40002205, 2025). "Together, these observations suggest that targeting IER2-induced senescent melanoma cells may improve therapeutic outcomes." (PMID 34611309, 2021). "We, therefore, reasoned that IER2 could conceivably promote melanoma progression through the induction of senescence and specific SASP components." (PMID 34611309, 2021). "This could conceivably reflect heterogeneity in the melanoma cell populations, yet this seems unlikely, as the IER2-inducible cells underwent two rounds of single-cell cloning before experiments were performed." (PMID 34611309, 2021). "To investigate whether IER2 might play a similar role in human melanoma, we analyzed the TCGA skin cutaneous melanoma dataset." (PMID 34611309, 2021). "To determine whether IER2 expression correlates with the proliferative or the invasive potential of melanoma cells, we analyzed a dataset of human melanoma cell lines utilizing the Heuristic Online Phenotype Prediction algorithm (HOPP)." (PMID 34611309, 2021). "We also investigated whether the nuclear localization of IER2 promotes melanoma invasion." (PMID 34611309, 2021). "Furthermore, senescent cells exhibit resistance to apoptosis, and IER2-induced senescence may therefore render melanoma cells intrinsically resistant to chemotherapy-induced apoptosis, as well as through the production of OPN in the SASP." (PMID 34611309, 2021). "A major component of the IER2-driven SASP is osteopontin (OPN), which plays a central role in driving melanoma cell invasion." (PMID 34611309, 2021). "This analysis demonstrated a significant upregulation of both IER2 and OPN protein expression in primary melanomas, compared to MN, and further upregulation of OPN in distant metastases (for clinicopathological data)." (PMID 34611309, 2021). "OPN secreted by IER2-expressing senescent cells stimulated the migration and invasion of non-senescent melanoma cells." (PMID 36834846, 2023).
melanoma (continued). "To investigate the relationship between IER2 and OPN expression during melanoma progression, we analyzed tissue microarrays (TMAs) containing human melanocytic nevi (MN), primary melanomas (primary tumors, PT), and distant melanoma metastasis (DM)." (PMID 34611309, 2021). "IER2, the IER2-induced SASP including OPN, as well as IER2-induced senescent cells themselves may therefore represent therapeutic targets in melanoma." (PMID 34611309, 2021). "Again, expression of IER2-wt strongly promoted melanoma cell invasion, whereas expression of IER2-mNLS even suppressed invasion, rather than promoting it." (PMID 34611309, 2021). "Immuno-staining of serial sections revealed co-expression of IER2 and OPN in melanoma nests." (PMID 34611309, 2021). "However, an EGR1 -like pattern of gene expression was observed for JUN, indicating that the intensity of expression of the EGR1, FOS, IER2, and JUN transcription factor genes could be coregulated at least in some human melanomas." (PMID 39436655, 2024). "In addition to IER5, IER5L and IER2—two homologues of IER5 with structural similarity —are also highly expressed and promote tumor progression, metastasis, and invasion in various cancers including prostate cancer, non-small cell lung cancer, melanoma, and colorectal cancer." (PMID 40002205, 2025). "Consistently, we found that OPN in the IER2-induced SASP produced by senescent melanoma cells is able to stimulate the motility and invasion of non-senescent melanoma cells in a paracrine manner." (PMID 34611309, 2021).
colorectal cancer (3 papers, 2021 to 2026). A primary or metastatic malignant neoplasm that affects the colon or rectum. "IER2 promotes metastasis and is associated with poor prognosis in colorectal cancer patients." (PMID 34611309, 2021). "We have previously identified MACC1 and IER2 as functional biomarkers in the context of colorectal cancer." (PMID 41897334, 2026). "Taken together, these findings show a functional interplay between the colorectal biomarkers MACC1 and IER2, which, in turn, has an impact on the survival of colorectal cancer patients." (PMID 41897334, 2026).
chordoma (2 papers, 2024 to 2025). Chordomas are rare malignant tumors arising from embryonic remnants of the notochord in axial skeleton. "Hypoxic microenvironment reprogramed CAFs into ERS-CAF subtype, which can regulates SPP1macrophage to aggravate chordoma progression via the IER2/GMFG/ITGB1 axis in chordoma." (PMID 41425545, 2025). "Overexpression of IER2 in CAFs promotes chordoma progression, which can be impeded by IER2 knockdown or use of ERS inhibitors." (PMID 39207055, 2024). "We uncovered that hypoxic and ERS‐CAF signature scores as well as the expression of IER2 were significantly positively correlated with the immune cells abundance (especially macrophage) within the chordoma microenvironment." (PMID 39207055, 2024). "The hypoxic chordoma microenvironment induces upregulation of IER2 in CAF to stimulate its ERS effect and then release GMFG cytokine." (PMID 39207055, 2024). "Collectively, the findings suggest that ERS‐CAF regulates SPP1+ macrophage to aggravate chordoma progression via the IER2/GMFG/ITGB1 axis, which may be targeted therapeutically in future." (PMID 39207055, 2024). "Given the crucial role of ERS‐CAF in chordoma progression, these findings together imply that IER2 may affect chordoma progression by regulating the ERS process of CAF within the tumor microenvironment." (PMID 39207055, 2024). "The current study demonstrated that the hypoxic chordoma microenvironment could induce sustained expression of IER2 in CAF to stimulate its ERS effect and then released GMFG cytokine." (PMID 39207055, 2024). "In addition, our analyses indicated a crucial role for hypoxia‐induced IER2 upregulation in ERS‐CAF formation, which was also closely linked to clinical features and prognosis of chordoma." (PMID 39207055, 2024).
gastric cancer (2 papers, 2022 to 2025). A primary or metastatic malignant neoplasm involving the stomach. "IER5 and its family members IER5L and IER2 have been reported to be overexpressed in many cancers including ovarian, hepatic, lung, and gastric cancers." (PMID 40002205, 2025). "F nucleatum-induced neutrophil transcriptional activation may be implicated in gastric cancer via several candidate genes including DNAJB1, EHD1, IER2, CANX, and PH4B among the top genes of interest." (PMID 36033825, 2022). "F nucleatum-induced neutrophil transcriptional activation may be implicated in gastric cancer via several candidate genes including DNAJB1, EHD1, IER2, CANX, and PH4B." (PMID 36033825, 2022).
Anxiety (1 paper, 2021). Intense feelings of nervousness, tension, or panic often arise in response to interpersonal stresses. "Interestingly, among the anxiety- and depression-related DEGs, we found the upregulation of Bcl3, C3, Gpat3, and Tnf in the AMY as well as the increased expression of Crhr2, Nant, Sar1a, and Tgif1 and the decreased expression of Ier2, Il12a, Nrep, and Tnfrsf25 in the ACC." (PMID 33898422, 2021).
asthma (1 paper, 2023). "In the present study, we screened seven key genes using the LASSO algorithm and identified differentially expressed genes, namely, CD300E and IER2, with AUC values greater than 0.7 as diagnostic markers for asthma using ROC curve analysis." (PMID 37259023, 2023). "This study explored a potential lncRNA-miRNA-mRNA regulatory network and its underlying diagnostic biomarkers (CD300E and IER2) in asthma and identified the immune cells most associated with them, providing possible diagnostic markers and immunotherapeutic targets for asthma." (PMID 37259023, 2023). "Finally, we investigated the association between the immune cell ratio and the expression of LUCAT1, MIR222HG, CD300E, and IER2 in patients with asthma to determine the biomarkers correlated with the immune cell ratio." (PMID 37259023, 2023). "We screened seven candidate diagnostic biomarkers for asthma using LASSO regression (namely, BCL10, CD300E, IER2, MMP13, OAF, TBC1D3, and TMEM151A), among which the area under the curve (AUC) value for CD300E and IER2 were 0.722 and 0.856, respectively." (PMID 37259023, 2023). "In this study, we screened key asthma-related genes (LUCAT1, MIR222HG, CD300E, and IER2) and immune cell infiltration profiles through bioinformatic analysis, which could provide insights into the pathogenesis of asthma and new perspectives and approaches for asthma diagnosis and treatment." (PMID 37259023, 2023). "Finally, we revealed the infiltration ratio of different immune cells in asthma and found a correlation between LUCAT1, MIR222HG, CD300E, and IER2 with some immune cells." (PMID 37259023, 2023). "Although CD300E and IER2 have not been reported in the context of asthma, CD300E serves as a biomarker for M2c macrophages." (PMID 37259023, 2023).
bladder cancer (1 paper, 2024). "Recent research has identified the PCAT19 as a crucial regulator in the malignant progression of bladder cancer through the miR-335-5p/IER2 axis." (PMID 39744012, 2024).
heart failure (1 paper, 2020). Inability of the heart to pump blood at an adequate rate to meet tissue metabolic requirements. "Microarray results also revealed common induction of transcription factor-coding genes whose modulation in response to CPB has not been described, among which IER2, IER3, and FOSL2 play critical role in cardiac remodeling and apopotosis, myocardial dysfunction, and heart failure." (PMID 31924244, 2020).
lung adenocarcinoma (1 paper, 2017). A carcinoma that arises from the lung and is characterized by the presence of malignant glandular epithelial cells. "We noticed that in lung adenocarcinoma samples, many EGF-inducible genes, including FOS and IER2 are downregulated whereas EINCR1 expression is generally upregulated." (PMID 28732076, 2017).
ovarian carcinoma (1 paper, 2025). A malignant neoplasm originating from the surface ovarian epithelium. "Furthermore, analysis of data from an ovarian cancer mouse model seeded by OSE or FTE showed that higher expression of Ier5 is observed in ovarian cancer cells of OSE origin, whereas higher expression of Ier5l and Ier2 is observed in those derived from FTE." (PMID 40002205, 2025). "Further, since other IER5 family genes (IER2 and IER5L) have also been reported to regulate HSF1 activity, this family of genes may collectively be involved in the progression of ovarian cancer via the HSF1 pathway." (PMID 40002205, 2025). "We found that Ier5 expression is elevated in ovarian cancer derived from OSE but not FTE, whereas both Ier5l and Ier2 were upregulated in those from FTE but not OSE." (PMID 40002205, 2025).
Sepsis (1 paper, 2024). Sepsis is defined as life-threatening organ dysfunction caused by a dysregulated host response to infection. "IER2 was significantly higher expressed in late sepsis patients who rapidly recovered compared to acutely septic patients." (PMID 38720891, 2024).